RN7SL222P (RNA, 7SL, cytoplasmic 222, pseudogene)
Gene: Miscellaneous RNA gene on chromosome 11 (100,641,975 to 100,642,273, reverse strand). Ensembl gene ENSG00000242165.
Homologues: Orthologues: chimpanzee Metazoa_SRP (97% identical), macaque Metazoa_SRP (90% identical). Paralogues in human: RN7SL1 (80% identical), RN7SL2 (79% identical), RN7SL3 (79% identical), RN7SL664P (77% identical), RN7SL49P (77% identical), RN7SL230P (77% identical), RN7SL44P (77% identical), Metazoa_SRP (76% identical), RN7SL408P (76% identical), RN7SL113P (76% identical), RN7SL278P (76% identical), RN7SL218P (75% identical), and 704 more.